SLC25A32 (solute carrier family 25 member 32)
Description:
Facilitates flavin adenine dinucleotide (FAD) translocation across the mitochondrial inner membrane into the mitochondrial matrix where it acts as a redox cofactor to assist flavoenzyme activities in fundamental metabolic processes including fatty acid beta-oxidation, amino acid and choline metabolism as well as mitochondrial electron transportation. In particular, provides FAD to DLD dehydrogenase of the glycine cleavage system, part of mitochondrial one-carbon metabolic pathway involved in neural tube closure in early embryogenesis.
Synonyms: MFT; MFTC; GLYB; RREI
Tractability: Antibody: UniProt predicts a signal peptide or a membrane-spanning region. PROTAC: ubiquitination databases record sites on it; its protein half-life has been measured.
Gene: Protein-coding gene on chromosome 8 (103,398,635 to 103,415,189, reverse strand). Ensembl gene ENSG00000164933.
Subcellular location: Mitochondrion inner membrane
Subcellular location (Human Protein Atlas): Mitochondria; Nucleoplasm
Pathways (Reactome):
Metabolism: Metabolism of folate and pterines
Gene Ontology:
Molecular function: FAD transmembrane transporter activity; folic acid transmembrane transporter activity; nucleotide transmembrane transporter activity
Biological process: mitochondrial FAD transmembrane transport; folic acid metabolic process; transmembrane transport; folic acid transport; nucleotide transport
Cellular component: mitochondrial inner membrane; mitochondrion
Genetic constraint (gnomAD): Loss-of-function variants: 23 observed, 29.38 expected, observed/expected ratio (o/e) 0.78, 90% interval 0.56 to 1.11. The upper end of that interval is the gene's LOEUF score, 1.11, which puts it in group 4 of 6, group 1 being the genes least tolerant of losing a copy. Missense variants: 309 observed, 356.51 expected, observed/expected ratio (o/e) 0.87, 90% interval 0.79 to 0.95. Synonymous variants: 152 observed, 141.81 expected, observed/expected ratio (o/e) 1.07, 90% interval 0.94 to 1.23.
Homologues: Orthologues: chimpanzee SLC25A32 (100% identical), macaque SLC25A32 (98% identical), rabbit SLC25A32 (96% identical), dog SLC25A32 (94% identical), pig SLC25A32 (92% identical), mouse Slc25a32 (90% identical), guinea pig SLC25A32 (89% identical), rat Slc25a32 (87% identical), zebrafish slc25a32b (69% identical), tropical clawed frog slc25a32 (67% identical), zebrafish slc25a32a (64% identical), Drosophila melanogaster CG8026 (55% identical), and 1 more. Paralogues in human: SLC25A5 (27% identical), SLC25A6 (27% identical), SLC25A4 (26% identical), SLC25A36 (25% identical), SLC25A31 (24% identical), SLC25A12 (23% identical), SLC25A23 (23% identical), SLC25A13 (23% identical), SLC25A24 (23% identical), SLC25A29 (23% identical), SLC25A33 (23% identical), SLC25A30 (22% identical), and 37 more.
Diseases named in the same sentence as SLC25A32 in open-access papers:
SLC25A32 is named in the same sentence as 35 diseases in open-access papers, as found by Europe PMC text mining. Sharing a sentence is not in itself a finding about the gene and the disease. The quoted sentences say what the papers report.
glioblastoma (3 papers, 2023 to 2024). The most malignant astrocytic tumor (WHO grade IV). "In glioblastoma, SLC25A32 promotes cell proliferation, colony and spheroid formation, and induces an invasive phenotype in the glioblastoma cell line GBM#BG5, primarily through the activation of the PI3K-AKT-mTOR signaling pathway." (PMID 39795950, 2024). "Notably, we obtained mutation frequency data that are almost consistent with the UALCAN database because both have high SLC25A32 mutation frequency in lung adenocarcinoma, endometrial, HNSC, stomach, breast, colorectal, glioblastoma, and ovarian serous cystadenocarcinoma (OV)." (PMID 39624160, 2024). "SLC25A32 expression level was positively correlated with MSI in most cancers, such as UCEC, SKCM, LUAD, and glioblastoma multiforme (GBM)." (PMID 39624160, 2024). "Analysing the SLC25A32 protein expression level data from the CPTAC database in the UALCAN platform revealed that SLC25A32 protein expression increased over SLC25A32 in OV, UCEC, lung cancer, HNSC, and liver cancer and decreased over SLC25A32 in PAAD and glioblastoma." (PMID 39624160, 2024). "However, the mechanism and function of SLC25A32 in the progression of human glioblastoma (GBM) remain unclear." (PMID 37365560, 2023).
liver cancer (3 papers, 2020 to 2024). An epithelial or non-epithelial malignant neoplasm that arises from the liver. "At SLC25A32, 6.3% of liver cancer patients have evidence of Neanderthal introgression compared to 0.2% of non-affected individuals." (PMID 36503519, 2022). "In East Asians, SLC25A32 had a higher proportion of Neanderthal introgression among liver cancer patients compared to the general population." (PMID 36503519, 2022). "Strong correlation between SLC25A32 amplification and mRNA expression was observed across different tumor types including breast, ovarian and liver cancer." (PMID 32166001, 2020).
multiple acyl-CoA dehydrogenase deficiency (3 papers, 2017 to 2023). "Existing research has shown that the reduction or mutation of SLC25A32 may induce multiple acyl-CoA dehydrogenase deficiency, human myelomeningocele, MADD and related deficiencies, riboflavin-responsive exercise intolerance, neural tube defects and other diseases." (PMID 37365560, 2023).
breast carcinoma (2 papers, 2020 to 2024). "We preliminarily demonstrated the influence and underlying mechanism of SLC25A32 on biological tumour behaviour in breast cancer via functional and pathway experiments on proliferation, invasion, and migration." (PMID 39624160, 2024). "This study aimed to reveal SLC25A32 as a novel prognostic biomarker for pan-cancer prediction and immunotherapy efficacy and specifically describes its underlying mechanism of action in breast cancer." (PMID 39624160, 2024). "Second, despite conducting multiple functional experiments to verify the possible role and mechanism of SLC25A32 in breast cancer, in vitro experiments and immune infiltration of SLC25A32 and immunotherapy are lacking." (PMID 39624160, 2024). "The LinkedOmics platform and Metascape were used to further analyse the gene and functional enrichment of SLC25A32 co-expressed in breast cancer." (PMID 39624160, 2024). "Here, a systematic bioinformatics analysis combined with experiments can validate SLC25A32 as an innovative pan-cancer prognostic and immune-related biomarker and reveal its targetable mechanism of action in breast cancer." (PMID 39624160, 2024). "Bioinformatics analysis revealed the role of SLC25A32 in breast cancer, and we further explored its biological function." (PMID 39624160, 2024). "Thereafter, we investigated the specific regulatory mechanism of SLC25A32 in breast cancer progression." (PMID 39624160, 2024). "SLC25A32 was found to be highly amplified in different tumor types with highest incidence in breast cancer (44.8%), neuroendocrine prostate cancer (30%), ovarian serous cystadenocarcinoma (22%) and liver hepatocellular carcinoma (16.1%)." (PMID 32166001, 2020). "In addition, string and bubble plots visualised the GO/KEGG analysis and revealed other functional roles of SLC25A32 in breast cancer." (PMID 39624160, 2024). "Similarly, the median survival of breast cancer patients bearing SLC25A32 amplification was also reduced by 42 months." (PMID 32166001, 2020). "In addition, although we have conducted bioinformatics studies on a variety of pan-cancers, our experimental data are only limited to breast cancer, and the inference of the experimental results of SLC25A32 to pan-cancers is limited, and more experiments are needed to verify it in the future." (PMID 39624160, 2024). "GSEA revealed that SLC25A32 was enriched in PI3KAKTMTORSIGNALING _PATHWAY and EXTRACELcLULAR_ MATRIX_ ORGANIZATION pathways in breast cancer." (PMID 39624160, 2024). "SLC25A32 expression and the prognostic significance of copy number alterations in multiple cancers were compared using the UCSCXenaShiny and GEPIA2.0 platforms, and its specific function in breast cancer was experimentally verified." (PMID 39624160, 2024).
colon cancer (2 papers, 2022 to 2025). "It was stated that mutations in SLC25A15 and SLC25A32 occurred at a higher frequency in patients with colon cancer than in healthy individuals." (PMID 41465541, 2025).
adrenocortical carcinoma (1 paper, 2024). "SLC25A32 was significantly associated with the pathological stage of adrenocortical carcinoma (ACC), KICH, KIRP, lung adenocarcinoma (LUAD), and uterine carcinosarcoma (USC)." (PMID 39624160, 2024).
bladder urothelial Carcinoma (1 paper, 2024). "In BRCA, bladder urothelial Carcinoma (BLCA), HNSC, LUAD, Sarcoma (SARC), THCA, and UCEC SLC25A32 promoter methylation differed between normal tissues." (PMID 39624160, 2024).
breast invasive carcinoma (1 paper, 2024). "Otherwise, UALCAN results indicate that expression of SLC25A32 and SHMT2 correlates with overall survival in breast invasive carcinoma." (PMID 39125744, 2024).
breast tumour (1 paper, 2024). "SLC25A32 knockdown decreased breast tumour cell proliferation, invasion, and metastasis." (PMID 39624160, 2024).
glioma (1 paper, 2023). A benign or malignant brain and spinal cord tumor that arises from glial cells (astrocytes, oligodendrocytes, ependymal cells). "Elevated expression of SLC25A32 was observed in GBM, and high SLC25A32 expression was associated with a high glioma grade and poorer prognosis." (PMID 37365560, 2023). "In this study, we confirmed that SLC25A32 is highly expressed in glioma compared to normal brain tissue." (PMID 37365560, 2023). "The results showed that SLC25A32 was low in normal brain tissue, but increased with the increasing of glioma grade." (PMID 37365560, 2023). "SLC25A32 immunohistochemistry (IHC) was performed on glioma (n = 18) and normal brain tissue samples (n = 3) collected from Qilu Hospital." (PMID 37365560, 2023). "Through univariate Cox regression analysis of CGGA gene expression profile, the effects of the SLC25A32 expression level and other clinical characteristics on the survival of glioma patients were found." (PMID 37365560, 2023). "Moreover, the upregulation of SLC25A32 correlated with tumor histological grades in glioma and poorer prognosis." (PMID 37365560, 2023). "The findings above indicated that increased SLC25A32 expression was connected to higher grade gliomas and could serve as a prognostic indicator for GBM patients." (PMID 37365560, 2023). "The RNA level of SLC25A32 in glioma cell lines was also higher than that in normal astrocytes." (PMID 37365560, 2023). "Moreover, SLC25A32 protein expression level increased with the increase of glioma grade." (PMID 37365560, 2023). "SLC25A32 plays a role in tumor progression, but research on SLC25A32 in glioma is still lacking." (PMID 37365560, 2023).
metabolic myopathies (1 paper, 2018). "No other causative mutations associated with metabolic myopathies or inherited neuropathies were found in the target gene kits including the ETFA, ETFB, flavin adenine dinucleotide synthetase 1 (FLAD1), and solute carrier family 25 member 32 (SLC25A32) genes." (PMID 30587156, 2018).
neural tube defect (1 paper, 2024). A congenital defect characterized by failure of the neural tube to close completely; this results in the presence of openings in the brain or spinal cord. "Allelic alterations in SLC25A32 may lead to neural tube defects (NTD) in human fetuses, and SLC25A32 knockout mice may also develop neurological diseases in the embryonic period." (PMID 39624160, 2024).
ovarian carcinoma (1 paper, 2020). A malignant neoplasm originating from the surface ovarian epithelium. "More specifically, median survival of ovarian cancer patients exhibiting SLC25A32 gene amplification was 39.85 months as opposed to 48.72 median months survival for patients with no SLC25A32 amplification." (PMID 32166001, 2020).
pulmonary fibrosis (1 paper, 2023). Chronic progressive interstitial lung disorder characterized by the replacement of the lung tissue by connective tissue, leading to progressive dyspnea, respiratory failure, or right heart failure. "Folate supplementation elevated the expression of MTHFD2 and SLC25A32, alleviated oxidative stress and effectively suppressed myofibroblast formation and silica-induced pulmonary fibrosis in mice." (PMID 37280614, 2023). "Folate supplementation elevated the expression of MTHFD2 and SLC25A32, alleviated oxidative stress and effectively suppressed myofibroblast differentiation and silica-induced pulmonary fibrosis in mice." (PMID 37280614, 2023). "Importantly, folate supplementation elevated the expression of MTHFD2 and SLC25A32, suppressed TGF-β induced oxidative stress and effectively mitigated myofibroblast formation and silica-induced pulmonary fibrosis in mice." (PMID 37280614, 2023).
thymoma (1 paper, 2024). A neoplasm arising from the epithelial cells of the thymus. "Tumour-associated fibroblast infiltration was positively correlated with SLC25A32 expression in CHOL, HNSC, KIRP, MESO, thymoma (THYM), UCS, and PAAD." (PMID 39624160, 2024).
tumor (6 papers, 2020 to 2025). "Folate metabolism is regulated by SLC25A32 in Chinese hamster ovary cells, and monocarbon and folate metabolism have been previously linked to tumour growth." (PMID 39624160, 2024). "To further analyse the SLC25A32 proteomics data, we investigated the possible post-translational modification sites of SLC25A32 and the mutation frequency in various tumour types using the PhosphpSitePlus database." (PMID 39624160, 2024). "SLC25A32 is significantly associated with the survival prognosis of some cancers, immune infiltrating cells, tumour stemness, and immune-related markers." (PMID 39624160, 2024). "Our experimental results showed that LY294002 inhibited the proliferation and invasion of tumor cells caused by SLC25A32." (PMID 37365560, 2023). "In conclusion, SLC25A32 expression may be closely associated with the malignant biological functions of most cancer types, promoting tumour cell metastasis and proliferation and inhibiting DNA damage repair." (PMID 39624160, 2024). "Meanwhile, the reduction or mutation of SLC25A32 affects the progression of the tumor." (PMID 37365560, 2023). "In ACC and KICH, higher SLC25A32 transcript level expression predicted worse tumour stage and clinical manifestations." (PMID 39624160, 2024). "We analysed the correlation data using the CancerSEA database to explore the relationship between SLC25A32 expression at the single-cell level and the biological behaviour and function of most tumours." (PMID 39624160, 2024). "SLC25A32 expression is positively correlated with the malignant biological functions of most tumours, including metastasis, differentiation, inflammation, angiogenesis, apoptosis, cell proliferation, stemness, and epithelial–mesenchymal transition (EMT)." (PMID 39624160, 2024). "Beyond the controversial substrate specificity of SLC25A32, its role in tumour progression is rarely discussed." (PMID 39624160, 2024). "Meanwhile, in the future, we expect to analyze multiomics data and calculate Jaccard similarity coefficient to explore the level of heterogeneity of SLC25A32 between tumours and patients to increase the clinical translation prospects in different tumours." (PMID 39624160, 2024). "The differential expression of SLC25A32 in multiple tumours and corresponding healthy tissues at transcript levels was investigated using the TIMER2.0, GEPIA, and UALCAN databases." (PMID 39624160, 2024). "Evaluation of the genes co-expressed with SLC25A32 revealed the possible mechanism of SLC25A32 in tumour progression." (PMID 39624160, 2024). "It should be noted that there is great intertumoral heterogeneity among different tumours, and the application of results for SLC25A32 needs to be rigorous and limited." (PMID 39624160, 2024). "In conclusion, the molecular foundation for the reduction of tumor development by SLC25A32 knockdown is through the PI3K-AKT-mTOR signaling pathway." (PMID 37365560, 2023). "Meanwhile, previous study has demonstrated that the THF transporter of SLC25A32 is highly expressed in varying tumors, and obviously facilitated tumor cell growth to reduce patients' survival, whereas downregulation of SLC25A32 inhibits tumor cell propagation." (PMID 35265266, 2022). "To investigate the role of SLC25A32 as a potential cancer target we assessed the effect of SLC25A32 knock-down on the proliferation of a panel of tumor cell lines of different origins." (PMID 32166001, 2020). "Our results indicate that BSO synergizes with SLC25A32 knock-down in inhibiting cell proliferation and producing ROS only in SLC25A32-sensitive tumor cells." (PMID 32166001, 2020). "In the present report, we show that SLC25A32 is highly amplified in a wide range of human tumor samples and that gene amplification correlates with reduced overall survival of cancer patients." (PMID 32166001, 2020). "Therefore, we extracted the correlation between SLC25A32 expression and stemness scores of different tumour types." (PMID 39624160, 2024).